CNIH4 (cornichon family member 4)
Description:
Involved in G protein-coupled receptors (GPCRs) trafficking from the endoplasmic reticulum to the cell surface; it promotes the exit of GPCRs from the early secretory pathway, likely through interaction with the COPII machinery.
Synonyms: CNIH-4; HSPC163
Tractability: Antibody: UniProt predicts a signal peptide or a membrane-spanning region. PROTAC: its protein half-life has been measured.
Gene: Protein-coding gene on chromosome 1 (224,356,858 to 224,379,459, forward strand). Ensembl gene ENSG00000143771.
Subcellular location: Membrane; Endoplasmic reticulum; Endoplasmic reticulum-Golgi intermediate compartment
Gene Ontology:
Molecular function: CCR5 chemokine receptor binding; protein binding; signaling receptor binding
Biological process: endoplasmic reticulum to Golgi vesicle-mediated transport; vesicle-mediated transport
Cellular component: endoplasmic reticulum; endoplasmic reticulum-Golgi intermediate compartment; COPII-coated ER to Golgi transport vesicle; endoplasmic reticulum membrane; membrane
Genetic constraint (gnomAD): Loss-of-function variants: 3 observed, 9.49 expected, observed/expected ratio (o/e) 0.32, 90% interval 0.14 to 0.82. That is too few expected variants to judge how well the gene tolerates losing a copy. Missense variants: 99 observed, 105.26 expected, observed/expected ratio (o/e) 0.94, 90% interval 0.8 to 1.11. Synonymous variants: 39 observed, 35.12 expected, observed/expected ratio (o/e) 1.11, 90% interval 0.86 to 1.45.
Homologues: Orthologues: chimpanzee CNIH4 (99% identical), macaque CNIH4 (99% identical), rabbit CNIH4 (97% identical), dog CNIH4 (96% identical), guinea pig CNIH4 (96% identical), mouse Cnih4 (96% identical), rat Cnih4 (94% identical), pig CNIH4 (91% identical), tropical clawed frog cnih4 (89% identical), zebrafish cnih4 (55% identical), Drosophila melanogaster cnir (45% identical). Paralogues in human: CNIH1 (37% identical), CNIH3 (32% identical), CNIH2 (31% identical), PPCS (15% identical).
Diseases named in the same sentence as CNIH4 in open-access papers:
CNIH4 is named in the same sentence as 19 diseases in open-access papers, as found by Europe PMC text mining. Sharing a sentence is not in itself a finding about the gene and the disease. The quoted sentences say what the papers report.
glioma (5 papers, 2023 to 2025). A benign or malignant brain and spinal cord tumor that arises from glial cells (astrocytes, oligodendrocytes, ependymal cells). "Bioinformatic analysis revealed that CNIH4 participates in glioma malignancy, stemness‐like processes, immunotherapy response, and chemotherapy sensitivity." (PMID 37062068, 2023). "We demonstrated that CNIH4 has a significant effect on GSC markers (CD144, CD44, and BMI1) via knocking down CNIH4 by using specific shRNAs, implying that CNIH4 as a definite therapeutic target in glioma stem cells." (PMID 37062068, 2023). "The expression level of CNIH4 expression was measured in human astrocytes (HA) and human glioma (LN229, T98, U251, and U87) cell lines." (PMID 37062068, 2023). "We noted that CNIH4 was up‐regulated in glioma tissues, GSCs, and further elevated in TMZ‐resistant cell lines." (PMID 37062068, 2023). "A significant increase in CNIH4 mRNA was also observed in TMZ‐resistant glioma cells derived from two GEO microarray data cohorts (GSE53014 and GSE68029), implying its role in chemoresistance." (PMID 37062068, 2023). "Upregulated CNIH4 expression was more prevalent in advanced gliomas." (PMID 37062068, 2023). "We also utilized GSEA to determine the functional relevance of CNIH4 expression in glioma." (PMID 37062068, 2023). "In transwell assays, knockdown of CNIH4 impaired glioma cell migration and invasion." (PMID 37062068, 2023). "To summarize, CNIH4 potentially plays roles in glioma TIME and may guide current glioma therapy." (PMID 37062068, 2023). "Studies such as those on SCN3B in glioma, CDK2 in glioma, AIMP1 in head-neck squamous cell carcinoma and CNIH4 in head and neck squamous cell carcinoma demonstrate the diverse applications of TCGA data in cancer research." (PMID 40290723, 2025). "For example, discovering the role of single gene in a single tumor, they argued in detail the identity of SCN3B and CDK2 in glioma, and proved the role of AIMP1, CNIH4 in head and neck squamous cell carcinoma." (PMID 40108724, 2025). "While TCGA has revolutionized cancer biomarker discovery, exemplified by studies identifying SCN3B in glioma, CDK2 in glioma prognosis, AIMP1/CNIH4 in head-neck squamous carcinoma, and RAD50 in breast cancer, its limitations must be acknowledged." (PMID 40860678, 2025). "Furthermore, CNIH4 silencing was revealed to dramatically enhanced TMZ sensitivity and apoptosis, while inhibiting proliferation, migration /invasion, sphere‐formation, as well as tumorigenicity in glioma cells." (PMID 37062068, 2023). "However, as a key component of vesicle trafficking‐related genes (VRGs), Cornichon family AMPA receptor auxiliary protein 4 (CNIH4) has not been systematically elucidated in glioma so far." (PMID 37062068, 2023).
cervical carcinoma (4 papers, 2022 to 2025). A carcinoma arising from either the exocervical squamous epithelium or the endocervical glandular epithelium. "In summary, CNIH4 is markedly upregulated in cervical cancer and its high expression correlates with a poor prognosis." (PMID 38087815, 2023). "Notably, CNIH4 overexpression is linked to adverse outcomes in low-grade glioma (LGG) and cervical cancer, and its expression in cervical cancer is associated with tumor progression and the inhibition of ferroptosis." (PMID 40051704, 2025). "In addition, Cornichon family AMPA receptor auxiliary protein 4 (CNIH4) is upregulated in cervical cancer, CHIH4 promotes tumor progression by inhibiting ferroptosis by enhancing SLC7A11-mediated cystine import, boosting glutathione synthesis and GPX4 activity." (PMID 40895556, 2025). "Silencing CNIH4 or SLC7A11 restores ferroptotic sensitivity, identifying CNIH4 as a potential prognostic biomarker and therapeutic target in cervical cancer." (PMID 40895556, 2025).
colon cancer (4 papers, 2019 to 2025). "TMED9 drives colon cancer metastasis via the CNIH4/TGFα/GLI pathway, inducing EMT and enhancing migration/invasion." (PMID 41373732, 2025). "CNIH4 gene, which encodes a member of CORNICHON family, an evolutionarily conserved TGFα exporter, is essential for metastasis of colon cancer cells." (PMID 33934539, 2021). "Analyses in three colon cancer cell types highlight a TMED9-dependent gene set that includes CNIH4, a member of the CORNICHON family of TGFα exporters." (PMID 31253868, 2019). "Our data indicate that TGFA and CNIH4, which display predictive value for disease-free survival, promote colon cancer cell metastatic behavior, and suggest that TMED9 pro-metastatic function involves the modulation of the secretion of TGFα ligand." (PMID 31253868, 2019). "Lastly, TMED9 was shown to mediate colon cancer metastases by activating the GLI1, CNIH4 and TGFA regulatory pathway and opposing TMED3-WNT-TCF signaling." (PMID 40497947, 2025).
gastric cancer (3 papers, 2023 to 2025). A primary or metastatic malignant neoplasm involving the stomach. "CNIH4 is a long non-coding RNA that has been found to be downregulated in gastric cancer compared to normal tissue, but it has also been reported to facilitate migration in colorectal cancer cells." (PMID 37240204, 2023). "Moreover, CNIH4 has been shown to be significantly overexpressed in LIHC tissues and is significantly associated with gastric cancer cell proliferation, proposing it as a novel biomarker for ovarian cancer." (PMID 40051704, 2025). "Furthermore, knockdown of CNIH4 suppressed the proliferation of gastric cancer cells." (PMID 37062068, 2023).
breast carcinoma (2 papers, 2025). "Given the elevated CNIH4 expression in breast cancer and its impact on the cell cycle and proliferation, CNIH4 could emerge as a potential therapeutic target." (PMID 40051704, 2025). "Functional experimental outcomes demonstrated that CNIH4 knockdown led to an accumulation of cells in the G0/G1 phase, indicating that CNIH4 may promote breast cancer cell proliferation by modulating the cell cycle." (PMID 40051704, 2025).
ovarian carcinoma (2 papers, 2022 to 2025). A malignant neoplasm originating from the surface ovarian epithelium. "Although LIMCH1, CRLS1, CDT1, CNIH4 have been associated with various cancers, their relationship with ovarian cancer has been proposed in this study for the first time to the best of our knowledge." (PMID 36338962, 2022). "CNIH4, which was also a hub gene that played a pivotal role in the flow of information within OC network, has no reported association with ovarian cancer." (PMID 36338962, 2022). "Furthermore, LIMCH1, CRLS1, CDT1, and CNIH4 were found to be associated with various cancer types, but their roles in ovarian cancer have not been identified yet." (PMID 36338962, 2022). "As a result, six genes (CDT1, CNIH4, CRLS1, LIMCH1, POC1A, and SNX13), and two miRNAs (mir-147a, and mir-103a-3p) were suggested as novel candidate prognostic biomarkers for ovarian cancer." (PMID 36338962, 2022).
esophageal carcinoma (1 paper, 2025). A primary or metastatic malignant neoplasm involving the esophagus. "Differential expression analysis using TCGA data showed that CNIH4 was significantly upregulated in bladder urothelial carcinoma (BLCA), BRCA, and esophageal carcinoma (ESCA) cancers." (PMID 40051704, 2025).
Fibrolamellar carcinomas (1 paper, 2025). "CNIH4 was initially identified as significantly overexpressed in Fibrolamellar carcinomas, suggesting its potential as an oncogene." (PMID 40051704, 2025).
lung adenocarcinoma (1 paper, 2025). A carcinoma that arises from the lung and is characterized by the presence of malignant glandular epithelial cells. "Additionally, immunohistochemical analysis from the HPA database showed that CNIH4 protein was markedly overexpressed in various tumor types, including BLCA, BRCA, and lung adenocarcinoma (LUAD)." (PMID 40051704, 2025).
malignant glioma (1 paper, 2023). A grade III or grade IV glioma arising from the central nervous system. "CNIH4 was shown to be overexpressed in malignant glioma variants and was frequently observed in GCSs and TMZ‐resistant cell lines." (PMID 37062068, 2023).
tumor (8 papers, 2019 to 2025). "Functional enrichment analysis demonstrated significant associations between CNIH4 and multiple cancer-related pathways, notably those involved in cell cycle regulation and DNA repair, which are pivotal in tumor cell proliferation and survival." (PMID 40051704, 2025). "Furthermore, the cornichon family AMPA receptor auxiliary protein 4 (CNIH4) has been identified as a key cancer marker associated with stemness, cell cycle, DNA repair, invasion, and proliferation, with high expression in tumor cells." (PMID 39409886, 2024). "This study aims to further explore the relationship between the CNIH4 gene and tumor prognosis and immune microenvironment, to reveal the key role of CNIH4 in tumor development, and to evaluate its potential application in clinical diagnosis and treatment." (PMID 40051704, 2025). "Correlation analysis was highly consistent with the localization results, showing that CNIH4 expression levels were significantly and positively correlated with the tumor cell content in the spot." (PMID 40051704, 2025). "Our findings indicate that CNIH4 is upregulated in multiple cancers, corroborating previous research that has established a link between elevated CNIH4 expression and tumor malignancy." (PMID 40051704, 2025). "Knocking down CNIH4 significantly suppresses tumor growth as demonstrated in a nude mouse xenograft tumor model, providing evidence for the involvement of upregulated CNIH4 expression in the development of CESC." (PMID 38087815, 2023). "Higher expression of CNIH4 was found in advanced tumor and pathological stages, as well as lymph node metastasis." (PMID 38087815, 2023). "The expression of the CNIH4 gene in CESC tissues was considerably elevated compared to adjacent non‐tumor tissues in the TCGA‐CESC cohort." (PMID 38087815, 2023). "Our study identified CNIH4 as a potential VRG that regulates tumor stemness, microenvironment immunity, and chemotherapy sensitivity." (PMID 37062068, 2023). "In BRCA, CNIH4 was significantly and positively correlated with multiple cell cycle-related genes and proteins, suggesting a regulatory role for CNIH4 in cell cycle control and tumor cell proliferation." (PMID 40051704, 2025). "However, such precise regulatory mechanisms of CNIH4 expression in tumor immune microenvironment need to be elucidated in further studies." (PMID 38087815, 2023). "Notably, an increase in CNIH4 copy number was positively correlated with its mRNA expression level, which may drive further overexpression of CNIH4 in tumors and consequently impact tumor biology." (PMID 40051704, 2025). "Single gene localization analysis revealed that CNIH4 expression was similarly localized to tumor cells, suggesting that in BRCA, CNIH4 may be primarily expressed by tumor cells." (PMID 40051704, 2025). "Moreover, it keeps tumor growth local through repression of pro-metastatic TMED9-TGFα signaling via its downregulation of TMED9, CNIH4, TGFA, and GLI1." (PMID 31253868, 2019).
cancer (6 papers, 2022 to 2025). A tumor composed of atypical neoplastic, often pleomorphic cells that invade other tissues. "Through pan-cancer level expression pattern analysis, our study further substantiates CNIH4 as a universally associated oncogene." (PMID 40051704, 2025). "Additionally, high CNIH4 expression was associated with poor prognosis in various cancers, reinforcing the critical role of CNIH4 in oncogenesis and suggesting its potential as an independent prognostic marker." (PMID 40051704, 2025). "CNV analysis showed that CNIH4 has common amplification mutations in various cancers, which may be related to its elevated expression in tumors." (PMID 40051704, 2025). "The CNIH4 gene, an emerging biomarker, is increasingly recognized for its role in the malignant progression across various cancers." (PMID 40051704, 2025). "This study presents a comprehensive analysis of CNIH4, examining its expression patterns, genomic alterations, epigenetic modifications, prognostic significance, and interactions with the immune microenvironment across a spectrum of cancers." (PMID 40051704, 2025). "This study elucidates the multifaceted role of CNIH4 in oncogenesis by conducting a comprehensive analysis of its expression patterns, genomic alterations, epigenetic modifications, prognostic implications, and interactions with the immune microenvironment across various cancers." (PMID 40051704, 2025). "A significant negative correlation was observed between CNIH4 mRNA expression and methylation levels in various methylation probes in pan-cancer." (PMID 40051704, 2025).
neurological disease (1 paper, 2023). "Three target genes (CNIH4, MTUS1, and FES) were enriched in neurological disease-related network." (PMID 38092781, 2023).
CNIH4 also shares sentences with these, for which no sentence is quoted: head and neck squamous cell carcinoma (2 papers); breast adenocarcinoma (1); chronic myelogenous leukemia (1); colorectal cancer (1); liver cancer (1); skin melanoma (1).